Y_RNA (Y RNA )
Gene: Miscellaneous RNA gene on chromosome 7 (72,983,360 to 72,983,461, reverse strand). Ensembl gene ENSG00000276178.
Homologues: Orthologues: macaque Y_RNA (85% identical), guinea pig Y_RNA (83% identical), dog Y_RNA (75% identical). Paralogues in human: Y_RNA (100% identical), Y_RNA (95% identical), RNY3 (86% identical), Y_RNA (86% identical), RNY3P1 (85% identical), Y_RNA (85% identical), Y_RNA (84% identical), RNY3P14 (83% identical), Y_RNA (83% identical), Y_RNA (82% identical), RNY3P5 (81% identical), Y_RNA (81% identical), and 97 more.